PGR (progesterone receptor)
Diseases named in the same sentence as PGR in open-access papers (continued):
Sharing a sentence is not in itself a finding about the gene and the disease.
tumor (continued). "The present study aimed to ascertain a relationship between the expression of PD-L1 in the tumor, TILs, ER, PgR, and Her-2/neu." (PMID 36247496, 2022). "Across RWS, two reported PgR status of tumours; one of these found PgR status was a significant predictor of pCR on univariate analysis (p < 0.01) but not on multivariate analysis." (PMID 35833190, 2022). "The final diagnosis is based on immunohistochemical and cytogenetic tests to accurately assess tumor type, grade, estrogen receptor (ER), progesterone receptor (PR), and human epidermal growth factor receptor 2 (HER2) status." (PMID 35281118, 2022). "The molecular subtype evaluating the expression in tumor tissue of hormone receptors (estrogen receptor (ER) and progesterone receptor (PR)), human epidermal growth factor receptor type 2 (HER2) and Ki67 was considered." (PMID 36006065, 2022). "The tumor subtypes were classified by immunohistochemistry for expression of hormone receptors (estrogen receptor [ER] and progesterone receptor [PR]) and human epidermal growth factor receptor 2 (HER2)." (PMID 35353237, 2022). "The tumor was estrogen-(90% of cells, Allred score 8) and progesterone receptor-positive (40% of cells, Allred score 6), and the Ki67 proliferative index was 30% (30% of the nuclei of the tumor cells had a positive reaction)." (PMID 36197223, 2022). "In our multivariable analysis, a combination of menopause status, tumor grade, ER score, and PgR score independently predicted RS (accuracy: 0.800, 95% CI: 0.719–0.866) and RS > 25, respectively (accuracy: 0.858, 95% CI: 0.764–0.889)." (PMID 35887614, 2022). "Other studies supported the MSKCC nomogram findings that age, tumor size, histopathology, estrogen receptor status and progesterone receptor status were valuable predictors of SLN status." (PMID 35794594, 2022). "In EC, DSCAM-AS1 was associated with endometrial tumor promotor gene PRL and with expression of ERα and its target genes TFF1 and PGR." (PMID 35885035, 2022). "Hormonal therapy is most effective except for the patients with progesterone receptor less than 74 fmol and tumor grade I or progesterone receptor more than 74 fmol and tumor size greater than 26 mm and progesterone receptor greater than 320 fmol." (PMID 35785020, 2022). "Traditionally, tumor grade, tumor size, lymph node status, estrogen (ER), progesterone (PgR), and human epidermal growth factor (HER2/neu or c-erbB2) receptor status have represented the main prognostic markers for BC." (PMID 36428728, 2022). "In this context, we demonstrated in a large series of female and male patients with PTC that estrogen receptors α (ERα) and progesterone receptor (PR) were expressed in more than 65% of tumor tissues and correlated with larger tumor size at diagnosis." (PMID 36428608, 2022). "According to the American Society of Clinical Oncology (ASCO)/College of American Pathologists guidelines (CAP), ER and PgR assays are considered positive if at least 1% of the tumor cell nuclei in the sample are immunoreactive." (PMID 33670083, 2021). "Together, ESR1, ESR2, and PGR are likely closely correlated and have a role in multiple tumor genesis." (PMID 34322374, 2021). "Patient data (age, menopausal status, family history, hormone therapy), tumor MRI-features (location, margins, enhancement) and histological features (histological type, grading, ER, PgR, HER2, Ki-67 index) were collected." (PMID 34572862, 2021). "Firstly, the difference in the primary outcome of survival without local recurrence between TARGIT-IORT and EBRT was not significant for any of the tumour subgroups viz pathological tumour size, grade, ER status, PgR status, HER2 status and lymph node status." (PMID 34035435, 2021).
tumor (continued). "Treatment selection for Stage IV BC is guided by tumor expression of targetable receptors, including the estrogen receptor (ER), progesterone receptor (PR), and the human epidermal growth factor receptor 2 (HER2)." (PMID 34295806, 2021). "ESR1 and PGR transcription levels were correlated with the tumor stage (p < 0.05), and the higher expression of ESR1 and ESR2 are associated with higher tumor stage." (PMID 34322374, 2021). "Fine needle aspiration biopsy confirmed fibrous and smooth muscle tissue in the tumor, and immunohistochemical examination found the estrogen receptor (ER) and progesterone receptor (PR) were positive." (PMID 33663124, 2021). "While tumor size and metastatic spread are of the utmost importance for prognosis, so are tumor grade, proliferation and expression of estrogen- (ER), progesterone- (PgR) and HER2-receptors, and these clinicopathological features guide therapy decision-making." (PMID 34930399, 2021). "We investigated the impact of tumour size, grade, ER, PgR, HER2 and lymph node status on local recurrence-free survival, and of local recurrence on distant relapse and mortality." (PMID 34035435, 2021). "In our study, the class of edema correlates significantly with tumor size, histological class, grading and expression of ER, PgR and HER2b, and Ki-67 index, reflecting how the presence of edema is associated with particularly aggressive tumors." (PMID 34572862, 2021). "Each CPRS quartile was characterized by a different patients’ composition, especially for age, lymph node involvement, tumor size, estrogen and progesterone receptor expression, and Ki-67." (PMID 34183674, 2021). "Genetic alterations and immunological effects of ESR1, ESR2, and PGR were analyzed using the cBioPortal and Tumor and Immune System Interaction Database (TISIDB), respectively." (PMID 34322374, 2021). "Conversely, when PgR is lost, another receptor, ERβ, down-regulates ERα target genes, whereas AR enhances ERα target gene transcription and potentially contributes to tumor growth." (PMID 34638241, 2021). "This study demonstrated that larger tumor size and lower progesterone receptor level at baseline and larger tumor size of postoperative were statistically significantly associated with worse DFS (p = 0.004, p = 0.021 and p = 0.001, respectively)." (PMID 34631568, 2021). "ER and PgR positivity were defined as positive nuclear staining in ≥ 1% of the invasive tumour cells; 75% of the patients had ER + tumours." (PMID 34453638, 2021). "Tumours that are ER positive are often also PgR positive; thus, the significance of PgR on its own is sometimes overlooked." (PMID 33226492, 2021). "Clearly, better methods are needed to determine the quantity and functional status of tumor ER, as well as PgR, in order to reliably identify patients most likely to benefit from ET." (PMID 33531464, 2021). "More importantly, essential data, such as the tumour size and grade, lymph node involvement, and hormonal receptor status (oestrogen receptor/progesterone receptor/HER2), were unavailable." (PMID 34044478, 2021). "Nevertheless, according to the American Society of Clinical Oncology/College of American Pathologists (ASCO/CAP) guidelines, in routine assessment BC is considered PgR(−) if <1% or 0% of tumor cell nuclei are immunoreactive." (PMID 34638241, 2021). "The main factors considered for initiating patients with IBC-NSTs on adjuvant or neoadjuvant chemotherapy are the tumor size, nodal status, nuclear grade, age, tumor subtype based on the results of IHC for ER, PgR, and HER2, and the Ki67 index." (PMID 35008357, 2021). "Patient details including age, tumour type, tumour size, tumour grading, estrogen receptor (ER)/progesterone receptor (PR)/human epidermal growth factor receptor 2 (HER2/neu) status and pathologic stage was studied." (PMID 34790485, 2021).
tumor (continued). "Tumour stage (P = 0.031∗χ2), ER negativity (ER-) (P = 0.009∗¶), PgR negativity (PgR-) (P = 0.006∗¶) and HER2 enriched molecular subtype (HER2) (P = 0.009∗¶) were all associated with achieving pCR in the breast." (PMID 34171619, 2021). "Overall, 214 tumours had positive PgR expression (84.6%), and the mean PgR score was 5.6 ± 2.1 (range: 0-8, median: 7)." (PMID 34177266, 2021). "Traditionally, tumor size; status of nodal metastasis; and status of the estrogen receptor (ER), progesterone receptor (PR), and HER2 were taken as useful prognostic biomarkers for BRCA in the clinic." (PMID 33688372, 2021). "Estrogen receptor (ER) and progesterone receptor (PR) positivity was defined as positive immunohistochemical staining in ≥1% of tumour cells." (PMID 33564308, 2021). "We tested it on 993 patients referred to our institute characterized by sentinel lymph node status, tumor size, age, histologic type, grading, expression of estrogen receptor, progesterone receptor, HER2, and Ki-67." (PMID 33477893, 2021). "Given the heterogeneity of the prognostic factors in the baseline demographics, predictive results are reported using multivariate Cox modeling, adjusted by age, nodal status, ER and PgR status, histological grade, and pathological tumor size." (PMID 34377934, 2021). "Overall, no statistical differences between the two populations were shown in terms of tumor characteristics (ER and PgR expression, HER2 overexpression, and proliferation index) and pathological stage." (PMID 34869002, 2021). "To examine the clinical relevance of ESR1, ESR2, and PGR in pan-cancer, we analyzed the correlations of their expression with tumor stage." (PMID 34322374, 2021). "As it shown, the patients were at the age of (63.8 ± 12.5) years, 86.0% (37/43) were likely to have tumour grade of I-II, 97.7% (42/43) were ER/progesterone receptor (ER/PR)-positive and 88.4% (38/43) were HER2-negative." (PMID 33828195, 2021). "Of the 314 patients, 307 had information for the clinical characteristics of the tumor as ER, 137 from Modena and 170 from Lecce, while 301 (131 from Modena and 170 from Lecce) had information about the PgR status." (PMID 34869002, 2021). "This study showed that the predictive factors affecting HER2 discrepancy in the no NAC group were related to menopause, breast surgery type, histologic grade, tumor size exceeding 2 cm, and ER/PgR negativity." (PMID 34149935, 2021). "Comamonas and Pseudoxanthomonas, which were abundant in BCM2, were negatively correlated with HR, ER, PgR, and ET in tumor tissues." (PMID 34584037, 2021). "Thirty-nine patients had stage IA (49%), tumour grades 1 + 2 were confirmed in 64 cases (80%) and tumours were ER or PgR positive in 86% and 79%, respectively." (PMID 34070058, 2021). "The difference in pathological features was not statistically significant among the three groups, which included tumor pathological type, T/N stage, total stage, estrogen receptor, progesterone receptor, HER-2 receptor status and adjuvant therapy." (PMID 33676505, 2021). "Correlation between IHC and tumor size, lymph node status, distance metastasis, estrogen receptor (ER), progesterone receptor (PR) and Her-2/neu was assessed." (PMID 34452576, 2021). "This tumor exhibits focal and moderate PgR expression, scant ER IR-cells, and low proliferation index." (PMID 33981288, 2021). "A significant correlation was found between tumor histologic class, grading, ER, PgR and HERb2 expression, and Ki-67 index." (PMID 34572862, 2021). "In the current analysis, it is unsurprising that histopathological and immunohistochemical characteristics such as PgR status, tumour grade and disease burden independently predict breast and axillary pCR, as described in several recent studies [15,]." (PMID 34171619, 2021). "A significant tamoxifen treatment benefit was observed among patients with larger tumors, lower tumor grades, and progesterone receptor–positive tumors." (PMID 34190995, 2021).
tumor (continued). "In univariate analysis, age, menopausal status, tumor grade, pathological type, tumor size, ER, PgR, HER2, Ki67, and molecular subtype were all found to be significantly associated with chemotherapy administration (P<0.001)." (PMID 33680973, 2021). "Tumours expressing progesterone receptor (PR) and/or estrogen receptor (ER) are considered hormone receptor-positive breast cancers, while in triple-negative breast cancer (TNBC), tumours do not express any of these receptors." (PMID 33413340, 2021). "The web calculator CancerMath (CM) allows you to estimate the probability of having positive lymph nodes valued on the basis of tumor size, age, histologic type, grading, expression of estrogen receptor, and progesterone receptor." (PMID 33477893, 2021). "Single-cell (sc) RNAseq of UCD65 primary tumours and metastases revealed that PGR expression was enriched in bone and brain metastatic lesions relative to primary tumours." (PMID 33144693, 2021). "Immunohistochemistry showed that 70% of tumor cells were positive for ER and 10% for progesterone receptor (PgR), the HER2-neu score was 0 and the Ki67 labeling index was 35%." (PMID 32541460, 2020). "The impact on concordance of prespecified features was assessed, including age, tumor size, intensity of ER and progesterone receptor (PR), grade, Ki67 and perineural and lymphovascular invasion." (PMID 32372569, 2020). "Immunohistochemistry (ER, PgR) was applied to suitable tumor sections and their status was evaluated semi-quantitatively by histopathologists using College American Pathologist (CAP) guidelines." (PMID 32944466, 2020). "There were no significant alpha diversity or phyla differences by estrogen/progesterone receptor status, tumor grade, stage, parity and body mass index." (PMID 32468338, 2020). "75% of the tumor samples are Estrogen Receptor/progesterone receptor positive (ER/PR+) and 55% have a Human Epidermal Growth Factor Receptor 2 positive (HER2+) status." (PMID 32040529, 2020). "American Joint Committee on Cancer (AJCC), 8th edition established a prognostic stage (PS) classification that not only included anatomical factors (T, N, and M), but also biological factors (tumor grade, ER, PgR, and HER2) in 2016." (PMID 32495291, 2020). "Tumor tissues were available for all patients with cancer, and the estrogen receptor/progesterone receptor and HER2 status was determined in these tissues as part of the routine clinical management." (PMID 33044511, 2020). "Especially, we examined the registrations on family history, menstruation, onset age, body mass index according to age, nodal status based on tumor size and subtype, and proportion based on ER, PgR, and HER2 status." (PMID 32394414, 2020). "Materials and Methods: Tumor samples tested for Estrogen receptor (ER) / progesterone receptor (PR) expression using immunohistochemical staining (IHC)." (PMID 32334485, 2020). "Oestrogen receptor (ER)/progesterone receptor (PgR)-positivity was found in 67.9% of cases, while 29.8% of patients had triple-negative tumours." (PMID 32488135, 2020). "For the distribution of clinicopathological parameters in this group of patients, including age, tumor size, histologic grade, estrogen receptor (ER), progesterone receptor (PR), HER2 status and metastasis location, please refer to our previous report." (PMID 32580421, 2020). "The RecQ Like Helicase (RECQL) gene has previously been shown to predispose to breast cancer mainly in European populations, in particular to estrogen receptor (ER) and/or progesterone receptor (PR) positive tumor." (PMID 33342430, 2020). "We also analyzed the patients stratified according to molecular subtypes (also based on the expression of ER, progesterone receptor (PR), and Her2), LN status, and tumor grade." (PMID 32708601, 2020).
tumor (continued). "Our primary endpoints for MET outcomes in vivo were proliferation (Ki67 immunostaining) and apoptotic (TUNEL assay) status and changes in nuclear levels of tumor biomarker proteins ERα, PGR, KLF9, and PTEN." (PMID 32046384, 2020). "A significant relation between survival time and the variables such as age, size of tumor, number of lymph nodes, stage, histological grade, estrogen receptor, progesterone receptor, and lymphovascular invasion was observed." (PMID 32461942, 2020). "In PgR-positive tumor cells, progesterone induces up-regulation of RANKL and enhances proliferation." (PMID 32947901, 2020). "Breast cancer treatment is based on the individual tumor’s expression of specific markers as estrogen receptor (ER), progesterone receptor (PR), human epidermal growth factor receptor (HER) 2,the proliferation marker Ki-67, and the extent of the disease." (PMID 32979150, 2020). "ER-/PgR- tumors showed a higher histologic grade, greater tumor size, and more lymph node involvement by metastasis." (PMID 32944466, 2020). "We evaluated tumor grade, lymph node, and estrogen receptor (ER), progesterone receptor (PR), human epidermal growth factor receptor 2 (HER2), and Ki67 as histologic biomarkers." (PMID 33256820, 2020). "ER- and PgR- tumors showed a higher histologic grade, greater tumor size, and more lymph node involvement by metastasis." (PMID 32944466, 2020). "Mammographic tumour appearance in relation to status for oestrogen receptor (ER), progesterone receptor (PR), human epidermal growth factor receptor 2, histological grade, Ki67 and molecular subtype was analysed using various regression models." (PMID 33257731, 2020). "Significant decreased in ESR1 and PGR signal was also detected after 10 days of culture in tumour L6 and L9, respectively." (PMID 32251338, 2020). "Traditional classification systems have been based on tumor size, lymph node involvement, histological grade, age, and estrogen receptor (ER), progesterone receptor (PR), and human epidermal growth factor receptor 2 (HER2) status." (PMID 33233830, 2020). "These biomarkers included tumor grade, estrogen receptor (ER), progesterone receptor (PgR), and human epidermal growth factor receptor 2 (HER2), and are used for the prediction of prognosis." (PMID 32495291, 2020). "Intratumor heterogeneity exists in the presence of tumor cell clones with different ERα and/or PgR expression within the same tumor lesion." (PMID 33316954, 2020). "In accordance with this, miRNAs predicted to be downregulated in fluids from PgR+ vs PgR− tumor were almost exclusively found within this module." (PMID 32605588, 2020). "The tumour sample of this patient was AR+, ER+ and PGR+; the histological subtype was low grade serous and the response lasted for 47 weeks." (PMID 33854564, 2020). "The overall tumor biology of breast cancer subtypes is highly dependent on the expression of estrogen receptor (ER), progesterone receptor (PR) and the human epidermal growth factor receptor 2 (HER2)." (PMID 32710281, 2020). "A hormone receptor-positive tumor is the breast cancer that has theses following receptors, estrogen receptor (ER), progesterone receptor (PR), and epidermal growth factor receptor (HER-2/Neu)." (PMID 32155880, 2020). "Hormonal receptor status of tumour tissue was subsequently tested centrally; 29/40 (72.5%) patients were AR+ (>10% staining tumour cells) (two samples unavailable), 35/37 (95%) ER+ and 25/37 (68%) PGR+ (five samples undetermined)." (PMID 33854564, 2020). "A significant relation was observed between survival time and the variables such as age, size of tumor, number of lymph nodes, stage, histological grade, estrogen receptor, progesterone receptor, and lymphovascular invasion." (PMID 32461942, 2020).